ICOS (inducible T cell costimulator)
Diseases named in the same sentence as ICOS in open-access papers (continued):
Sharing a sentence is not in itself a finding about the gene and the disease.
melanoma (continued). "In melanoma, treatment with anti-CTLA-4 Ab induces an increase of ICOS+ effector T cells, indicating that the ICOS/B7h pathway is required for antitumor responses." (PMID 30669702, 2019). "For example, it has been demonstrated that an increased frequency of blood-circulating ICOS+ CD4+ T cells, sustained over a period of 12 weeks of anti-CTLA-4 therapy, correlates with favorable clinical outcome in melanoma patients." (PMID 29494517, 2018). "In another study, Wang and colleagues observed an upregulation of Ki67, ICOS, and GATA3 in blood CD4+ and CD8+ T cells of anti-CTLA-4 antibody-treated melanoma patients." (PMID 29494517, 2018). "Regarding immunological parameters, a significant increase in T-cell ICOS expression (costimulatory molecule, third member of the CD28/CTLA-4 family) following ipilimumab treatment was found in melanoma patients who experienced disease control." (PMID 26337719, 2015). "Melanomas without metastases (NM) showed more expression of ICOS compared to tumors from the OOM group." (PMID 40621453, 2025). "In melanoma models, Treg accumulation may be driven by IL-2 produced by CD8+ T cells, which leads to upregulation of inducible T cell costimulator (ICOS), a co-stimulatory and anti-apoptotic molecule." (PMID 39534873, 2024). "A375 melanoma cells displayed low to absent ICOS baseline protein and mRNA expression shown by flow cytometry, qRT-PCR, and IHC." (PMID 37259155, 2023). "Our analyses of RNA-sequencing data from melanoma cell lines and single-cell RNA-sequencing data obtained from melanoma tumor tissue showed that the majority of melanomas do not express ICOS mRNA." (PMID 37259155, 2023). "Considering the inverse correlation with mRNA expression, ICOS negative melanomas tend to have an improved prognosis compared to ICOS expressing tumors." (PMID 37259155, 2023). "Additionally, the potential value of various new inhibitory immune checkpoints (BTLA, B7 family, IDO-1, LAG-3) and costimulatory molecules (GITR, ICOS, OX40, 4-1BB, CD40, CD27) has been confirmed for melanoma treatments." (PMID 36125617, 2022). "In one study, melanoma patients with the highest fold expansions of these ICOS+ Treg-like cells following TIL therapy and HD-IL-2 were noted to have worse clinical outcomes than patients with fewer ICOS+ Tregs." (PMID 34512641, 2021). "ICOS, a T-cell costimulatory molecule of the CTLA-4/PD-1/CD28 family, plays a nonoverlapping function with CD28 and is highly expressed by TA-Tregs in breast carcinoma, ovarian carcinoma, follicular lymphoma, melanoma, RCC and gastric cancer." (PMID 33924428, 2021). "The efficacy of CTLA-4 inhibition in melanoma bearing mice was significantly reduced in mice lacking either ICOS or its ligand." (PMID 32970735, 2020). "Furthermore, it has been demonstrated that an increased frequency of ICOS+ CD4+ T cells, sustained over a period of 12 weeks of anti-CTLA-4 therapy, correlates with improved OS in melanoma patients." (PMID 29494517, 2018). "The reasons for lack of response to IL-2 are starting to emerge: a recent study found that the T cell subset most induced by IL-2 in melanoma patients is regulatory T cells (Treg) expressing positive for CD4, CD25, Foxp3 and the inducible T cell costimulator (ICOS)." (PMID 24743024, 2014). "The circulating and tumor-infiltrating iNKT cells from melanoma patients showed elevated proportions of iNKTreg cells and exhibited higher levels of activation markers, NKR/NKG2 (such as NKG2A, NKG2C, and NKG2D), and ICP (particularly ICOS, TIM3, and/or LAG3) compared with the control groups." (PMID 41562072, 2025). "In Braf/Pten melanoma-draining LNs, TSLP promoted not only GATA3+ Th2 cells, but also GATA3+ Tregs expressing a specific signature including ST2, CCR8, ICOS, PD-1, CTLA-4, OX40, and IL-10 — but not Th2 cytokines IL-4 and IL-13." (PMID 36107619, 2022).
melanoma (continued). "Activation and cell cycle cGEPs were elevated in pretreatment nonresponders of melanoma and NMSC (meta-analysis P < 0.05 for CellCycle-G2M, CellCycle-Late-S, TIMD4/TIM3, exhaustion, ICOS/CD38, OX40/EBI3 and HLA) and in the combined CRC cohort (P < 0.05 for all)." (PMID 40903640, 2025). "Since CHI3L1 null mutation or a-CHI3L1 neutralizing antibody treatment reduced metastatic spread, they do not determine if the inhibition of ICOS and ICOSL and or the induction of CTLA-4 are due to the direct effects of CHI3L1 or due to the decreased metastatic spread of melanoma." (PMID 36618349, 2022).
autoimmune disease (45 papers, 2005 to 2026). A disorder resulting from loss of function or tissue destruction of an organ or multiple organs, arising from humoral or cellular immune responses of the individual to their own tissue constituents. "Dysregulation of the ICOS/ICOSL system has been implicated in several autoimmune diseases, including MS." (PMID 38473756, 2024). "Elevated ICOS expression is also associated with autoimmune diseases such as rheumatoid arthritis and lupus nephritis." (PMID 39691709, 2024). "Improper function of the ICOS/ICOSL pathway has been implicated in several autoimmune diseases, including multiple sclerosis (MS)." (PMID 38473756, 2024). "Dysregulated ICOS/ICOSL signaling is intimately associated with the pathogenesis of autoimmune diseases." (PMID 36405702, 2022). "Although polymorphisms in ICOS are associated with several autoimmune diseases, few studies have investigated the role of ICOS in primary Sjögren’s syndrome." (PMID 35723338, 2022). "Polymorphisms in ICOS have been associated with susceptibility to autoimmune diseases such as coeliac disease, pemphigus, and autoimmune hepatitis type 1." (PMID 35723338, 2022). "SNPs in the CD28/CTLA4/ICOS gene region were reported to be associated with several autoimmune diseases including, type-1 diabetes, systemic lupus erythematosus, autoimmune thyroid diseases and celiac disease." (PMID 22911710, 2012). "Studies with ICOS knockout mice and ICOS deficient patients have shown the importance of ICOS signaling for the development and effector function of different T cell subsets, indicating its crucial role in the regulation of immune responses in autoimmune diseases for both Tregs and Tresps." (PMID 38427068, 2024). "Blocking ICOS/ICOS-L signaling in RA has shown potential to reduce Tfh-mediated inflammation, highlighting ICOS as a therapeutic target in autoimmune diseases with Tfh dysregulation." (PMID 40283219, 2025). "ICOS-KO mice develop an exacerbated form of chronic EAE but are relatively resistant to other autoimmune diseases, such as experimental autoimmune myasthenia gravis and collagen-induced arthritis." (PMID 38473756, 2024). "As the co-stimulator regulating the proliferation, differentiation, and effective function of T cells, especially Treg and Tfh, the upregulation or downregulation of ICOS is closely correlated with the development of autoimmune diseases." (PMID 37325657, 2023). "Altogether, these interactions point to the importance of ICOS interactions, which have been found to have relevance in multiple autoimmune diseases." (PMID 35371081, 2022). "Increased numbers of ICOS+ TFH cells in peripheral blood are detectable in patients with autoimmune diseases including SLE, SjD, RA, and autoimmune thyroid diseases." (PMID 36311777, 2022). "Earlier it has been identified that ICOS, CTLA4 and CCR6 polymorphism is related to autoimmune disease risk in patients with Sarcoidosis28–30." (PMID 35075176, 2022). "The co-stimulatory and co-inhibitory molecules CTLA-4 and ICOS are involved in the pathogenesis of autoimmune disease." (PMID 35222353, 2021). "The expression of ICOS has been observed to be upregulated in many autoimmune diseases, allergic diseases and different types of neoplasms." (PMID 32983168, 2020). "In this review, we discuss the complicated role of ICOS+ Tregs in several classical autoimmune diseases, allergic diseases, and cancers and investigate the related therapeutic applications in these diseases." (PMID 32983168, 2020). "Sufficient evidence has demonstrated that ICOS+ Tregs can serve as a biomarker for clinical outcome and be used in testing therapeutic responses, not only in autoimmune diseases but also in tumors." (PMID 32983168, 2020). "Four genes CTLA4, IL2RA, ICOS, and IL7R have been associated with a group of autoimmune diseases in GWAS and with autoimmunity in the HPO database." (PMID 31695696, 2019).
autoimmune disease (continued). "Modulation of ICOS signaling has the potential to mitigate disease severity for a number of human autoimmune disorders." (PMID 27559335, 2016). "On the contrary, ICOS overexpression induces overproduction of CXCR5+CD4+TFH cells and causes exuberant GC responses and remarkably promotes antibody production with autoimmune disease in mice." (PMID 26491701, 2015). "Accumulating evidence indicates that ICOS is involved in the immunopathogenesis of animal models of various autoimmune disorders, including SLE, rheumatoid arthritis, multiple sclerosis and asthma." (PMID 16563187, 2006). "It should be noted that the genomic region 2q33 linked to autoimmune disease contains cluster of three genes encoding costimulatory molecules CTLA-4, CD28 and inducible costimulator (ICOS)." (PMID 15762980, 2005). "Therapeutic strategies aimed at disrupting Tfh–B-cell interactions, blocking Tfh-derived cytokines, or modulating co-stimulatory pathways (e.g., ICOS and PD-1) may offer effective means of managing autoimmune diseases driven by Tfh-cell dysregulation." (PMID 40283219, 2025). "Thus, modulation of ICOS signaling has the potential to mitigate disease severity in some human autoimmune disorders." (PMID 35224111, 2022). "Anti-ICOS/ICOSL mAb treatment may be a potential therapeutic option for some refractory or severe autoimmune diseases." (PMID 32983168, 2020). "For autoimmune diseases, the use of ICOS as a therapeutic target is still being explored." (PMID 32983168, 2020). "This suggests that dual antagonism of CD28 and ICOS could be particularly advantageous in autoimmune diseases where development of auto-antibodies contributes to pathogenesis since this process is particularly dependent on the contribution of Tfh cells." (PMID 32038630, 2019). "ICOS expression correlates with PD-1 expression on cTFH in both health and autoimmune disease." (PMID 30303980, 2018). "Finally, we address the link between ICOS and human autoimmune disorders and evaluate potential therapies aiming to mitigate disease progression by modulating ICOS signaling." (PMID 27559335, 2016). "Alterations in the cTfh compartment have been found in several ab-mediated autoimmune diseases, like SLE and RA, in which the expansion of cTfh cells (defined as CD4+CXCR5+PD-1+ICOS+ T cells) could be linked to disease activity." (PMID 26872212, 2016). "Thus, interfering with the ICOS signaling pathways may be a potential treatment for autoimmune diseases." (PMID 37325657, 2023). "Inducible T cell costimulator (ICOS) signalling is essential for follicular helper T (Tfh) cell activation and has emerged as a therapeutic target in B cell-dependent autoimmune diseases such as systemic lupus erythematosus (SLE)." (PMID 42270933, 2026). "Inducible costimulator (ICOS) and its ligand (ICOSL) are critical to regulate the immune response in autoimmune diseases." (PMID 36405702, 2022). "For instance, PD1 pathway was down-regulated in several autoimmune diseases such as RA, multiple sclerosis and T1DM, while inducible T cell costimulator (ICOS) is highly expressed in patients with SLE, IBD, or RA." (PMID 30842773, 2019). "It provides further rationale for targeting B cells and costimulatory pathways, such as ICOS and CD28, in autoimmune diseases by highlighting their potential to dampen autoreactive responses by eliminating both GC B cells and Tfh cells." (PMID 25101629, 2014). "By understanding these interactions, Tfh pathways may serve as potential therapeutic targets, with IL-21, ICOS, and PD1 blockades emerging as promising innovative therapeutic strategies to manage autoimmune diseases." (PMID 40283219, 2025). "Among the most studied immune checkpoints are cytotoxic T-lymphocyte antigen 4 (CTLA-4); programmed death-1 (PD-1) and its ligand, PD-L1; and inducible T-cell costimulator (ICOS), all of which are under active investigation in the context of autoimmune disorders, including RA." (PMID 41007749, 2025).
autoimmune disease (continued). "The interplay between costimulatory signals, such as ICOS/ICOSL, plays a key role in regulating T-cell activation and is believed to have a decisive influence in inciting and perpetuating cellular effector mechanisms in autoimmune diseases, such as MS." (PMID 38473756, 2024). "Taken together, we speculate that high levels of mTOR activation in T cells from ANA-positive patients contribute to autoantibody production by expanding effector T cells and PD1+ICOS+ TFH, which may eventually promote future development of autoimmune disease." (PMID 36311777, 2022). "This is somehow surprising, since the ICOS-ICOSL pathway is related to immune activation and inflammation, and therefore expected to mark the autoimmune disease rather than the associated vasculopathy." (PMID 35328257, 2022). "Although accumulating studies have indicated that ICOS and ICOSL could contribute to autoimmune diseases through their multiple functions, the precise role in the pathogenesis of RA remains unclear." (PMID 36405702, 2022). "While in healthy humans, expression of ICOS can be detected in 5–20% of circulating peripheral blood CD4 + T cells, studies showed that ICOS expression increases in patients with autoimmune diseases and is connected to increased pro-inflammatory cytokines expression." (PMID 33384022, 2020). "Our data suggest that ICOS plays an important role in the immunopathogenesis of SLE and support the possibility that blockade of the interaction between ICOS and B7RP-1 may have therapeutic value in treating this intractable autoimmune disorder." (PMID 16563187, 2006). "In our study, we found that CD160 was the most significant co-signaling gene aberrantly expressed in autoimmune diseases, while several widely-studied co-signaling genes, such as ICOS, PD1 and CLTA4, were not identified as significant genes in the RRA analysis." (PMID 30842773, 2019).
breast cancer (44 papers, 2011 to 2026). A primary or metastatic malignant neoplasm involving the breast. "As for breast cancer, ICOS gene polymorphisms were reported to be associated with the risk and characteristics of breast cancer in a Chinese patient cohort." (PMID 38127899, 2023). "The expression of ICOS in breast cancer is strongly associated with major clinical and molecular characteristics." (PMID 38127899, 2023). "ICOS expression has been described by infiltrating and proliferating tumor-associated Tregs in breast cancer, which is correlated with poor prognosis." (PMID 36157232, 2022). "It has been reported that ICOS positive immune cell infiltration is linked with poor prognosis of breast cancer and accounts for a strong predictor of disease." (PMID 31143539, 2019). "As we found that the ICOS expression is associated with a better prognosis for breast cancer patients, and positively correlated with immune cell sores, especially T-cell immune responses, but not for stromal cells, which suggests the varied role of ICOS expression in different tumors." (PMID 38127899, 2023). "Furthermore, ICOS-positive T cell infiltration was reported to be negatively associated with patient prognosis in breast cancer." (PMID 31143539, 2019). "This study first established that SNPs in the ICOS gene may affect breast cancer risk and some SNPs were also associated with clinical characteristics of breast cancer in Chinese women from northeast of China." (PMID 21917182, 2011). "Secondly, CT genotype and C allele might down-regulate the ICOS expression and then increase the breast cancer risk." (PMID 21917182, 2011). "This case-control study on the variants in the ICOS gene revealed that only rs10932029 may confer susceptibility to breast cancer." (PMID 21917182, 2011). "In addition, we found that ICOS gene polymorphisms were associated with clinicopathologic features of breast cancer patients." (PMID 21917182, 2011). "Although the polymorphisms in ICOS gene have been extensively studied in various diseases, including cancers, the association between ICOS gene polymorphisms and the risk of breast cancer remains unclear." (PMID 21917182, 2011). "The allograft breast cancer models revealed that only ICOS expression in T cell dynamically changed during tumor progression, and thus was possibly affected by other factors in the TME." (PMID 40708008, 2025). "Consistently, Icosl-KO breast cancer cell lines directly induce ICOS expression in CD4+ and CD8+ T cells." (PMID 40708008, 2025). "To explore the prognostic role of ICOS for breast cancer patients, we further analyzed the expression of ICOS and survival in a microarray dataset including a total of 8069 patients derived from the bc-GenExMiner v4.4 database." (PMID 38127899, 2023). "In breast cancer, the activation of ICOS and ICOSLG is closely related to the accumulation of Tregs cells and DCs, and is also an indispensable key factor in the activation of Tregs cells." (PMID 37842091, 2023). "After this, mammary tumor–bearing mice received daily doses of anti-ICOS, anti–PD-1, or anti–TIM-3 over 3 d to mitigate the confounding effects of these antibodies on other T cell subsets." (PMID 36480166, 2023). "In summary, ICOS correlates with higher malignant breast cancers, and it contributes to the regulation of the immune microenvironment of breast tumors, making it a potential biomarker and immunotherapy target." (PMID 38127899, 2023). "As we have found that ICOS expression is more likely to be overexpressed in more malignant breast cancer subtypes, we further investigate the prognostic role of ICOS in TNBC patients." (PMID 38127899, 2023). "In a breast cancer drug test, tremelimumab significantly increased the ratio of ICOS+/FoxP3+ CD4+ T cells in most patients and stablized the disease for more than 12 weeks in 42% of patients." (PMID 35799609, 2022).